OR52D1 (olfactory receptor family 52 subfamily D member 1)
Description:
Odorant receptor.
Synonyms: OR11-43
Tractability: Antibody: UniProt places it where antibodies can reach, with medium confidence; UniProt predicts a signal peptide or a membrane-spanning region; its Gene Ontology location is reachable by antibodies, with medium confidence.
Gene: Protein-coding gene on chromosome 11 (5,488,685 to 5,489,749, forward strand). Ensembl gene ENSG00000181609.
Subcellular location: Cell membrane
Pathways (Reactome):
Sensory Perception: Expression and translocation of olfactory receptors
Gene Ontology:
Molecular function: olfactory receptor activity; G protein-coupled receptor activity
Biological process: sensory perception of smell; detection of chemical stimulus involved in sensory perception of smell; G protein-coupled receptor signaling pathway; nervous system process
Cellular component: membrane; plasma membrane
Genetic constraint (gnomAD): Loss-of-function variants: 4 observed, 3.67 expected, observed/expected ratio (o/e) 1.09, 90% interval 0.51 to 1.87. That is too few expected variants to judge how well the gene tolerates losing a copy. Missense variants: 423 observed, 411.77 expected, observed/expected ratio (o/e) 1.03, 90% interval 0.95 to 1.11. Synonymous variants: 175 observed, 157.89 expected, observed/expected ratio (o/e) 1.11, 90% interval 0.98 to 1.26.
Homologues: Orthologues: chimpanzee OR52D1 (99% identical), rabbit OR52D1_2 (88% identical), guinea pig OR52D1 (86% identical), mouse Or52d1 (86% identical), rat Or52d1 (86% identical), rabbit OR52D1_1 (86% identical), tropical clawed frog or52d1 (52% identical), tropical clawed frog or52al1 (50% identical). Paralogues in human: OR52E8 (57% identical), OR52B2 (56% identical), OR52B6 (55% identical), OR52J3 (54% identical), OR52E6 (54% identical), OR52H1 (53% identical), OR52L1 (52% identical), OR52E2 (52% identical), OR52E4 (52% identical), OR52N2 (51% identical), OR52E5 (50% identical), OR52R1 (50% identical), and 39 more.